KDM2B (lysine demethylase 2B)
Description:
Histone demethylase that demethylates 'Lys-4' and 'Lys-36' of histone H3, thereby playing a central role in histone code. Preferentially demethylates trimethylated H3 'Lys-4' and dimethylated H3 'Lys-36' residue while it has weak or no activity for mono- and tri-methylated H3 'Lys-36'. Preferentially binds the transcribed region of ribosomal RNA and represses the transcription of ribosomal RNA genes which inhibits cell growth and proliferation. May also serve as a substrate-recognition component of the SCF (SKP1-CUL1-F-box protein)-type E3 ubiquitin ligase complex (Probable).
Synonyms: CXXC2; FBL10; FBXL10; JHDM1B; PCCX2; NEDCRO
Tractability: Small molecule: a high-quality ligand is known. PROTAC: UniProt records ubiquitination sites on it; ubiquitination databases record sites on it; its protein half-life has been measured; a small molecule that binds it is known.
Target class: Epigenetic regulator; Jumonji domain-containing; Eraser; Lysine demethylase
Gene: Protein-coding gene on chromosome 12 (121,429,096 to 121,582,279, reverse strand). Ensembl gene ENSG00000089094.
Subcellular location: Nucleus, nucleolus; Nucleus; Chromosome
Subcellular location (Human Protein Atlas): Nucleoplasm
Pathways (Reactome):
Chromatin organization: HDMs demethylate histones
Gene Ontology:
Molecular function: histone H3K36 demethylase activity; histone H3K36me/H3K36me2 demethylase activity; protein binding; unmethylated CpG binding; zinc ion binding; DNA binding; histone demethylase activity; transcription coregulator activity; RNA polymerase II cis-regulatory region sequence-specific DNA binding
Biological process: chromatin remodeling; embryonic camera-type eye morphogenesis; forebrain development; fourth ventricle development; heterochromatin formation; hindbrain development; initiation of neural tube closure; lateral ventricle development; midbrain development; midbrain-hindbrain boundary morphogenesis; negative regulation of DNA-templated transcription; negative regulation of neural precursor cell proliferation; negative regulation of neuron apoptotic process; negative regulation of transcription by RNA polymerase II; regulation of transcription by RNA polymerase II; SCF-dependent proteasomal ubiquitin-dependent protein catabolic process; spermatogenesis; third ventricle development
Cellular component: chromosome; nucleoplasm; nucleus; PcG protein complex; SCF ubiquitin ligase complex; chromatin; PRC1 complex; nucleolus
Genetic constraint (gnomAD): Loss-of-function variants: 25 observed, 131.42 expected, observed/expected ratio (o/e) 0.19, 90% interval 0.14 to 0.27. The upper end of that interval is the gene's LOEUF score, 0.27, which puts it in group 1 of 6, group 1 being the genes least tolerant of losing a copy. Missense variants: 1,235 observed, 1,767.9 expected, observed/expected ratio (o/e) 0.7, 90% interval 0.67 to 0.73. Synonymous variants: 715 observed, 711.69 expected, observed/expected ratio (o/e) 1, 90% interval 0.94 to 1.07.
Homologues: Orthologues: chimpanzee KDM2B (99% identical), dog KDM2B (95% identical), rabbit KDM2B (94% identical), macaque KDM2B (94% identical), rat Kdm2b (93% identical), mouse Kdm2b (92% identical), guinea pig KDM2B (91% identical), tropical clawed frog kdm2b (75% identical), zebrafish kdm2bb (63% identical), zebrafish kdm2ba (37% identical), Caenorhabditis elegans jmjd-1.2 (12% identical), Caenorhabditis elegans jmjd-1.1 (9% identical). Paralogues in human: KDM2A (47% identical), PHF8 (18% identical), KDM7A (18% identical), PHF2 (17% identical).
Diseases named in the same sentence as KDM2B in open-access papers:
KDM2B is named in the same sentence as 91 diseases in open-access papers, as found by Europe PMC text mining. Sharing a sentence is not in itself a finding about the gene and the disease. The quoted sentences say what the papers report.
breast carcinoma (12 papers, 2016 to 2024). "KDM2B inhibits senescence and, like ACBD3, is implicated in CSC self-renewal and Wnt/β-Catenin signaling in breast cancer." (PMID 36012147, 2022). "Overexpression of KDM2B was observed in breast cancer, lung cancer and gastric cancer, suggesting that KDM2B regulates cancer development." (PMID 34783291, 2021). "A potential oncogenic role of PRC1.1 is underlined by the fact that KDM2B is overexpressed in leukemias, breast cancer, and pancreatic cancer and conversely knockdown of KDM2B abrogated tumorigenicity." (PMID 34113809, 2021). "The oncogenic role of KDM2B has been reported in several human malignancies such as bladder cancer, breast cancer and pancreatic cancer." (PMID 34266408, 2021). "Another study reported NDY1/KDM2B functions as a master regulator of Polycomb complexes and controls the self-renewal of breast cancer stem cells." (PMID 33791221, 2021). "KDM2B is also required for maintenance of murine embryonic stem cells and breast cancer‐initiating cells." (PMID 29360266, 2018). "Basal marker and luminal marker analysis showed KDM2B is required for the maintenance of the myoepithelial/luminal progenitor cell phenotype of basal breast cancer cells." (PMID 26349457, 2016). "In breast cancer, downreguation of KDM2B inhibits anchorage-dependent and -independent growth, arrests cell cycle in G1 and promotes apoptosis, and CSCs were also reduced." (PMID 26349457, 2016). "RNA interference against KDM2B led to a massive induction of genotoxic stress, cell cycle arrest, and consequent apoptotic cell death, consistent with prior studies in pancreatic and breast cancers." (PMID 29360266, 2018).
pancreatic cancer (12 papers, 2016 to 2024). "But unexpectedly, KDM2B promoted K-RAS–mutated pancreatic cancer through upregulating a module of metabolic genes involved in OXPHOS in a mouse allograft model." (PMID 26989077, 2016). "Consistent with this theory, we have identified significant promoter hypomethylation of histone demethylase KDM2B in pancreatic cancer tissues." (PMID 39165427, 2024). "A study on pancreatic cancer showed that KDM2B bound to TSS, decreased the levels of H3K27me3, and regulated the expression of a series of genes, and ChIP-sequencing results showed that SAV1 is one of the potential target genes of KDM2B." (PMID 37033161, 2023). "Pancreatic cancer: High expression of KDM2B is seen in poorly differentiated pancreatic cancers (PANCS) and their metastases." (PMID 35406676, 2022). "In this paper, we have found an essential function of KDM2B as a component of variant PRC1 complex during TGF-β-induced EMT of A549 lung cancer and Panc1 pancreatic cancer cell lines." (PMID 33779563, 2021). "KDM2B was found to be overexpressed in pancreatic cancer, its expression being directly correlated with disease progression." (PMID 29156578, 2017). "Overexpression of KDM2B cooperated with KRAS oncogenic mutants (KRASG12D) to promote pancreatic cancer formation in mice." (PMID 29156578, 2017). "Thus, a recent study provided evidence that the deregulated expression of KDM2B, a member of the histone demethylase family, plays a relevant role in pancreatic cancer pathogenesis." (PMID 29156578, 2017). "In this report, we discovered that KDM2B, a member of variant PRC1 complex and also a histone H3 demethylase, epigenetically regulated the downregulation of several epithelial marker genes including CDH1, which was indispensable for TGF-β-induced EMT of lung and pancreatic cancer cells." (PMID 33779563, 2021). "KDM2B in EMT: KDM2B, also known as Ndy1, FBXL10, and JHDM1B, demethylates H3K36 and is overexpressed in human pancreatic cancer cells." (PMID 36902253, 2023). "KDM2B transcriptionally inhibits the expression of MOB1 and promotes pancreatic cancer migration and invasion by promoting Hippo signaling." (PMID 36902253, 2023). "This study revealed a novel functional significance of KDM2B in the epigenetic control of EMT process of lung and pancreatic cancer cells." (PMID 33779563, 2021). "Taken together, we concluded that KDM2B was indispensable for TGF-β-induced EMT process in A549 lung cancer and Panc1 pancreatic cancer cells." (PMID 33779563, 2021). "To validate the involvement of KDM2B in TGF-β-induced EMT process, we used two different cancer cell lines, A549 lung cancer and Panc1 pancreatic cancer cells, and treated them with TGF-β." (PMID 33779563, 2021). "In this study, we found that KDM2B was indispensable for TGF-β-induced EMT of A549 lung cancer and Panc1 pancreatic cancer cell lines." (PMID 33779563, 2021).
leukemia (9 papers, 2014 to 2023). A malignant (clonal) hematologic disorder, involving hematopoietic stem cells and characterized by the presence of primitive or atypical myeloid or lymphoid cells in the bone marrow and the blood. "Accordingly, some studies show how KDM2B is characterized by demethylase activity at H3K4me3 KDM2B has an important role in leukemia SC maintenance and proliferation of glioblastoma SCs." (PMID 39086963, 2022). "Various leukaemias and bladder cancers display up-regulated KDM2B and it is proposed to play a key role in leukaemia progression through loss of p15Ink4b function." (PMID 25145438, 2014). "Cancer-exome-sequencing endeavours have recently revealed that core components of the KDM2B/PRC1 complex, including KDM2B itself and BCOR/L1, are frequently mutated in a range of cancers, particularly leukemias." (PMID 24856970, 2014). "Data from murine models suggest that suppression of KDM2B in leukemia stem cells blocks the development of frank leukemia." (PMID 25225797, 2014). "Other studies showed that ectopic expression of KDM2B could antagonize KRAS-driven leukemias, while ablation led to an accelerated KRAS-driven myeloid transformation." (PMID 38028538, 2023). "For example, KDM2b/JHDM1b is important for regulating cell proliferation and senescence, is highly expressed in lymphoid and myeloid leukemias, and is reported to be an oncogene that plays critical roles in both leukemia stem cell self-renewal and leukemogenesis." (PMID 38028538, 2023). "It was also reported that KDM2B, as a bona fide oncogene, directly binds to and activates OXPHOS genes, not glycolytic-related genes, and subsequently contributes to the development of leukemia involving metabolic proliferative advantage." (PMID 26989077, 2016).
bladder cancer (8 papers, 2015 to 2023). "The molecular pathway for bladder cancer strongly appears to also involve expression of KDM2B, as well as the mTOR pathway." (PMID 36662841, 2023). "A similar NDY1/KDM2B-miR101-EZH2 axis was identified in bladder cancer." (PMID 28410242, 2017). "Exploring these links may help us understand the molecular mechanisms by which KDM2B, EZH2 and genetic alterations associated with bladder cancer may contribute to the oncogenic transformation of the human urothelia." (PMID 28515962, 2017). "The cancer genome atlas (TCGA) data showing a correlation between KDM2B and EZH2 expression and Oncomine data, showing a correlation between KDM2B and tumor progression, strongly support the role of the FGF-2/KDM2B/miR-101/EZH2 pathway in bladder cancer." (PMID 28515962, 2017). "The NDY1/KDM2B-miR-101-EZH2 axis has been identified as active in bladder cancer cells, wherein miR-101 suppresses the motility of T24 bladder cancer cells by targeting c-Met’s 3′-UTR." (PMID 25658842, 2015).
glioblastoma (7 papers, 2018 to 2023). The most malignant astrocytic tumor (WHO grade IV). "Collectively, our results demonstrate KDM2B is crucial for glioblastoma maintenance, with inhibition causing loss of GSC survival, genomic stability, and chemoresistance." (PMID 29360266, 2018). "KDM2B loss impaired glioblastoma cell viability, with greater impact in cells that express higher baseline levels of KDM2B." (PMID 29360266, 2018). "We observed induction of p21CIP1/WAF1 expression, as well as impaired the entry of glioblastoma cells into S‐phase after KDM2B loss." (PMID 29360266, 2018). "In addition, both siRNA‐mediated KDM2B loss as well as chemical inhibition using GSK‐J4 significantly sensitized tumor cells to chemotherapeutics used in clinical management of glioblastoma: lomustine and etoposide." (PMID 29360266, 2018). "Of note, the knockdown of KDM2B in glioblastoma cells decreases the levels of H3K36me2, reduces the number of proliferating cells and increase DNA damage accumulation, supporting KDM2B role in glioblastoma SC maintenance." (PMID 39086963, 2022). "Consistent with a previous study, KDM2B was highly expressed in glioblastoma stem cells (GSCs) compared to their differentiated counterparts." (PMID 33791221, 2021). "KDM2B dependency of glioblastoma cells is supported by the preferential sensitivity of KDM2Bhigh tumor cells to KDM2B inhibition compared to KDM2Blow tumor cells." (PMID 29360266, 2018). "Based on the efficacy of genetic targeting of KDM2B against glioblastoma, we investigated the efficacy of novel enzymatic inhibitors of KDM2B function." (PMID 29360266, 2018). "Here, we find that the chromatin regulator, JmjC domain histone H3K36me2/me1 demethylase KDM2B, is highly expressed in glioblastoma surgical specimens compared to normal brain." (PMID 29360266, 2018). "We found that KDM2B is expressed in glioblastoma and critically maintains glioblastoma cell survival, genome integrity, and stem‐like tumor populations." (PMID 29360266, 2018). "To interrogate the functional role of KDM2B in glioblastoma biology, we selected three representative primary cultures: KDM2B—high‐expressing cells (4121, 1587) and KDM2B—low‐expressing cells (T115)." (PMID 29360266, 2018). "Targeting KDM2B function genetically or pharmacologically impaired the survival of patient‐derived primary glioblastoma cells through the induction of DNA damage and apoptosis, sensitizing them to chemotherapy." (PMID 29360266, 2018). "GSK‐J4 treatment decreased glioblastoma cell viability in a concentration‐dependent manner, with two cultures expressing high KDM2B levels (4121 and 1587) displaying higher sensitivity compared to glioblastoma cultures expressing low KDM2B levels (T115) and normal astrocytes." (PMID 29360266, 2018). "Based on the overexpression and oncogenic function of KDM2B in systemic cancers that contain cancer stem cells, we investigated KDM2B as a molecular target in glioblastoma." (PMID 29360266, 2018). "In the present study, we examined the role of KDM2B in glioblastoma." (PMID 29360266, 2018). "Based on prior reports that GSCs are the most aggressive cellular population responsible for glioblastoma recurrence and the role of numerous KDMs in stem cell maintenance, we hypothesized specific function of KDM2B in GSCs." (PMID 29360266, 2018). "KDM2B knockdown or use of GSK-J4 inhibitors lowered the frequency, differentiation ability, and survival of glioblastoma stem-like cells, the inhibition of the DNA repair capacity of GBM cells, and chemoresistance." (PMID 37218871, 2023). "Glioblastoma (GBM): KDM2B plays a major role in the maintenance of glioblastoma cancer stem cells (GSCs) and knockdown of KDM2B induces apoptosis and DNA damage." (PMID 35406676, 2022). "Thus, we speculated that KDM2B may contribute to chemoresistance in glioblastoma." (PMID 29360266, 2018).
glioblastoma (continued). "Genetic KDM2B disruption augmented chemotherapy‐induced apoptosis, as measured by cleavage of PARP and caspase‐3, in all primary glioblastoma cultures tested." (PMID 29360266, 2018). "To interrogate KDM2B in the genomic stability and DNA repair capacity of glioblastoma, we targeted KDM2B with two nonoverlapping siRNA species (siKDM2B‐1 and siKDM2B‐2)." (PMID 29360266, 2018).
glioma (7 papers, 2018 to 2024). A benign or malignant brain and spinal cord tumor that arises from glial cells (astrocytes, oligodendrocytes, ependymal cells). "Another study showed that KDM2B overexpression was associated with poor prognosis in glioma and KDM2B knockdown inhibited cell proliferation and induced cell cycle arrest." (PMID 34220955, 2021). "KDM2B is highly expressed in glioma and GBM cells, and many studies have elucidated downstream targets and pathways." (PMID 39765675, 2024). "KDM2B had low cytoplasmic and mainly nuclear expression in both cell lines, in line with previous publication regarding KDM2B subcellular locations in glioma cells." (PMID 38903530, 2024). "KDM2B’s upregulation of the cell cycle in glioma also demonstrates a potential point of connection with AD, PD, and HD as cell cycle aberrations contribute to the development of neurodegenerative diseases." (PMID 39765675, 2024). "In glioma cell lines, silencing of KDM2B increased the expression of P21 and decreased the expression of cyclin D1, a pro-oncogene." (PMID 39765675, 2024). "Consistent with previous studies, KDM2B has been reported to be overexpressed in gastric cancer and glioma and its expression correlated with cancer progression." (PMID 33791221, 2021). "Validation in a broader cohort of patients was supported by an in silico analysis of the REMBRANDT glioma dataset, which showed a strong positive correlation between KDM2B expression with both CD133 and SOX2." (PMID 29360266, 2018). "Overcoming therapy resistance also involves TRAIL resistance of glioma tumor cells, and progress has been made even in this regard by sensitizing tumor cells to TRAIL-induced apoptosis through inhibition of KDM2B and eIF5B." (PMID 37626776, 2023). "Additionally, multiple KDM2A and KDM2B studies have demonstrated that miR-663a, miR-302a, and miR-let-7b downregulation resulted in the tumorigenesis of GBM and glioma." (PMID 39765675, 2024). "Given the role of KDM2B and PRC2 as oncogenes in brain cancer, further research should be carried out to determine whether the upregulation of KDM2B and PRC2 in glioma, GBM, and MB plays a combinatory role in the self-renewal properties of these pathologies." (PMID 39765675, 2024).
ovarian carcinoma (7 papers, 2018 to 2024). A malignant neoplasm originating from the surface ovarian epithelium. "Similarly, in ovarian cancer, overexpression of KDM2B is associated with poor prognosis, whereas a decrease in KDM2B expression is correlated with reduced proliferation and migration of cancer cells." (PMID 39239542, 2024). "Likewise, a similar KDM2B-H3K4me3-mediated EZH2 upregulation has been found in ovarian cancer cells." (PMID 34266408, 2021). "Therefore, EZH2 may also be regulated by KDM2B in ovarian cancer." (PMID 33163485, 2020).
pancreatic ductal adenocarcinoma (6 papers, 2019 to 2020). An infiltrating adenocarcinoma that arises from the epithelial cells of the pancreas. "In another study of pancreatic ductal adenocarcinoma, lysine demethylase 2 (KDM2B) suppressed the expression of MOB1 by its binding to the promoter region of MOB1, then YAP‐mediated transcription promoted the invasion, migration and proliferation of cancer cells." (PMID 32841529, 2020). "Studies of DNA methylation patterns revealed that lysine demethylase 2B (KDM2B) directly bound to the promoter region of HsMob1 gene, inhibited and promoted pancreatic ductal adenocarcinoma progression." (PMID 33255245, 2020).
acute myeloid leukemia (4 papers, 2011 to 2021). Acute myeloid leukemia (AML) is a group of neoplasms arising from precursor cells committed to the myeloid cell-line differentiation. "KDM2B overexpression induces transformation of hematopoietic progenitor cells in acute myeloid leukemia whereas reduction of KDM2B inhibited Hox9/Meis1 induced leukemic transformation." (PMID 34220955, 2021). "Consistent with overexpression of a H3K36me2-specific demethylase KDM2B in T-cell and B-cell acute lymphoblastic leukemia and in acute myeloid leukemia, we found its overexpression in almost all hematopoietic cell lines." (PMID 21886846, 2011).